ALK (ALK receptor tyrosine kinase)
Diseases named in the same sentence as ALK in open-access papers (continued):
Sharing a sentence is not in itself a finding about the gene and the disease.
tumor (continued). "The tumor cells are usually large and have diverse morphologies, express CD30, and the ALK-positive subtype also expresses the ALK protein." (PMID 40170733, 2025). "The combination of ALK inhibitors, like lorlatinib, with inhibitors of other pathways, such as CDK4/6 inhibitors, also holds promise for delaying resistance and enhancing tumor control." (PMID 39941694, 2025). "The selected biomarkers (EGFR, ALK, KRAS, and PDCD1), demonstrated significantly higher expression in NSCLC tumor tissues compared to adjacent normal tissues (p < 0.01)." (PMID 40927719, 2025). "Entinostat treatment significantly delayed or even prevented tumor development in pre-tumorigenic mice, despite the persistent activity of NPM::ALK signaling." (PMID 40175628, 2025). "In ALK-positive NSCLC patients, preclinical studies showed that the combination of AT13387 and crizotinib resulted in superior tumor inhibition and delayed resistance compared to crizotinib monotherapy." (PMID 40872476, 2025). "Treatment of NGP ALK KO xenografts with CDX0239-PBD led to rapid tumor growth in 3 xenografts and an initial transient response with subsequent rapid tumor growth in 2 xenografts." (PMID 40813394, 2025). "The tumor cell had a break in the intergenic sequence of the LOC388942 and a rearrangement with the 20–29 exons of the ALK." (PMID 40151836, 2025). "TKI-targeted inhibition of ALK can disrupt the EML4-ALK compartment, potentially interfering with the transcriptional regulation between MAPK and SWI/SNF, thereby affecting tumor cell proliferation." (PMID 40416876, 2025). "Lorlatinib, a third-generation ALK-TKI, developed to conquer acquired tumor resistance of generations 1 and 2 of ALK TKIs, was designed to penetrate blood–brain barriers with high potency on cancer cells that mutated." (PMID 40732249, 2025). "Gao et al26 synthesized a new ALK inhibitor called ZYY-B-2, which blocks the growth of tumor cells by inactivating downstream target proteins." (PMID 40584293, 2025). "AH cfDNA analysis further revealed multiple SCNAs restricted to the tumor, including duplications in MDM4, ALK, CCND3, and BRAF, as well as deletions in TFRC, FGF3, FGF9, and BRCA2." (PMID 41465072, 2025). "On the other hand, we report the somatic mutational landscape of HCC in our cohort, identified exclusively in the tumor tissues, with APC (100%), ALK (94%), HNF1A (56%), CDKN2A and HRAS (50%) emerging as the most frequently mutated genes." (PMID 41567639, 2025). "From The Cancer Genome Atlas (TCGA) and the Gene Expression Omnibus (GEO) databases, all available ROS1+ (n = 10), ALK+ (n = 5) and RET+ (n = 5) NSCLC tumor and ROS1+ cell line (n = 7) RNA-sequencing files were collected." (PMID 39737401, 2024). "APG-2449 is a triple kinase inhibitor of ALK, ROS1, and FAK that has shown anti-tumor activity in a mouse model of ALK/ROS1-positive NSCLC." (PMID 38474400, 2024). "Patients with tumors showing EGFR, ALK or ROS1 gene alterations were excluded, and the PD-L1 tumor proportion score was determined." (PMID 38539510, 2024). "More molecular targets such as anaplastic lymphoma kinase (ALK), ROS proto‐oncogene 1, receptor tyrosine kinase (ROS1), and v-raf murine sarcoma viral oncogene homolog B1 (BRAF) have shown promising anti-tumor efficacy." (PMID 38164287, 2024). "Next, in an effort to profile a ROS1+ specific expression signature, transcriptomes of ROS1+ tumor samples and ROS1+ patient-derived cell lines were compared to normal lung tissue or ALK/RET+ NSCLC specimens." (PMID 39737401, 2024). "Previous studies found that in patients with NSCLC harboring ALK rearrangement, high expression levels of YAP promoted resistance to ALK-TKIs, and the anti-tumor effect of ALK-TKIs was restored after YAP1 knockdown by siRNA in vivo and in vitro." (PMID 38499647, 2024).
tumor (continued). "Immunohistochemistry showed that tumor cells positively expressed vimentin, SMA, and Desmin usually, and CK, CD68, CD30 and ALK were partially expressed positively, while CD117 and CD34 were usually negative expressed." (PMID 39193013, 2024). "The resulting Cq values for the QfusionTM ALK, RET, or ROS1 fusion assays at a 15% tumor fraction were determined as 32.45 ± 0.17, 28.84 ± 0.25, and 25.27 ± 0.03, respectively." (PMID 38472960, 2024). "Strategies involving dual inhibition of ALK and other pathways, including MYC, Src, JNK/c-Jun, and Wnt/β-catenin, have demonstrated potential in overcoming resistance and hindering tumor growth in ALK+ cancers." (PMID 38397899, 2024). "ROS1 rearrangements, found in 1−2% of NSCLC patients, are identified as oncogenic drivers, creating a distinct molecular subgroup of NSCLCs since it is rare for ALK and ROS1 rearrangements to occur in the same tumor." (PMID 39335535, 2024). "Previous studies have demonstrated that kinases such as RET, MAP2K1, ALK, and FGF can promote tumor growth via helping tumor cells to evade the immune system by downregulating HLA-I expression." (PMID 38407266, 2024). "Immunohistochemical results showed that the tumor cells positively expressed smooth muscle actin (SMA), anaplastic lymphoma kinase (ALK), CD117, vimentin, but negatively expressed cytokeratin (CK), Desmin and Dog-1." (PMID 39193013, 2024). "Mechanistically, brigatinib exhibits selective binding affinity towards the ATP-binding domain of the ALK receptor tyrosine kinase, thereby inducing inhibition of ALK-mediated signaling pathways, consequently resulting in the demise of tumor cells." (PMID 38611728, 2024). "Interestingly, we observed increased viability and invasion in Hep3B and Huh7 cells upon RNase1 treatment, which could be repressed by pretreatment with crizotinib or Alectinib, suggesting that ALK is also essential for the biological activities of RNase1 in HCC tumor cells." (PMID 38307859, 2024). "To explore how ALKF1174L cooperates with MYCN to accelerate tumor growth, we performed RNA-seq on the MYCN and ALKF1174L/MYCN tumors (hereafter referred to as “ALK/MYCN”)." (PMID 38451815, 2024). "Anaplastic lymphoma kinase (ALK) and mesenchymal-epithelial transition factor (c-MET) are pivotal receptor tyrosine kinases involved in tumor proliferation." (PMID 39144632, 2024). "This action leads to dimerization and autophosphorylation of the ALK kinase domain and thus abnormally activates downstream signaling pathways, such as PI3K/AKT, JAK/STAT3, and RAS/ERK, finally acquiring tumor-formation activity." (PMID 37940761, 2024). "According to the present investigation, there is a statistical correlation between PD-L1 expression and factors such as tumor stage, histological type, co-occurrence of COPD, and ALK-positive." (PMID 39583517, 2024). "Immunophenotyping tests showed positivity of tumor cells for Desmin, Myogenin, MyoD1, Syna, CD56, and ALK." (PMID 38835374, 2024). "Bypass signaling pathway activation is an important category for ALK‐independent resistance, which might because of genetic alterations, dysregulation of autocrine signaling or feedback signaling, resulting in reactivation of downstream pathway required for tumor cell growth and survival." (PMID 39681089, 2024). "But based on the frequent detection of chromosomic alterations, especially near the anaplastic lymphoma kinase (ALK) gene, IMT is now considered to be a true neoplasm." (PMID 39498315, 2024). "First clinical evidence of MET exon 14 skipping tumours responding to a MET TKI was obtained in studies using crizotinib, an ATP-binding competitor of anaplastic lymphoma kinase (ALK), c-ros oncogene 1 (ROS1), RON, and MET." (PMID 38652103, 2024). "Immunohistochemical results showed that the tumor cells positively expressed vimentin, SMA, and ALK, which was consistent with the pathological diagnosis of IMT." (PMID 39193013, 2024).
tumor (continued). "Among ALK gene fusion-related neoplasms, SAMS is a recently reported tumor distinguished by the existence of myxoid spindle cell whorls and cords with co-expression of ALK, CD34, and S100 proteins." (PMID 39202049, 2024). "A therapeutic target for ATC is represented by anaplastic lymphoma kinase (ALK) rearrangements, involved in tumor growth." (PMID 38928438, 2024). "Biologic rational supports universal sensitivity of ALK TKI's agnostic of organ site of origin, as ALK fusions are exquisite tumour drivers." (PMID 39188081, 2024). "There are several ALK inhibitors are available for treatment of patients with ALK+ve advanced NSCLC and they have different clinical activity, intracranial tumour control, different toxicity profiles and different resistance patterns." (PMID 38439810, 2024). "Then, we assessed the significance of EP300 for the prognosis of LUAD by conducting Cox regression analysis of covariates, including gender, age, tumor size, tumor grade, T and N staging, and expression of PDL1, ALK, EGFR, and EP300." (PMID 38256128, 2024). "Our comprehensive proteogenomic analyses revealed a nuanced understanding of the tumor microenvironment in NSLA patients devoid of oncogenic EGFR and ALK alterations." (PMID 39300154, 2024). "Several ALK inhibitors are FDA-approved, and promising clinical effects with kinase inhibitors against ALK and ROS1 have been detected in several IMF tumor cases." (PMID 38611033, 2024). "Recent studies have shown that targeted oncogene therapy, which includes inhibitors of EGFR, ALK, KRAS, and BRAF, induces DNA double-strand breaks and activates the DDR pathway in residual tumor cells." (PMID 38776912, 2024). "The MDK/LRP1, MDK/ALK, GAS6/MERTK, and GAS6/AXL were identified as potential ligand-receptor pairs involved in the interactions between fibroblasts/endothelial cells and tumor cells." (PMID 37733241, 2023). "Based on the tumor responses in subgroups of patients, crizotinib was incorporated into the most recent COG study ANBL1531 for patients with ALK-aberrant tumors." (PMID 37835416, 2023). "The precise relationships between Tregs and tumour cells and between exhausted CD8+ T cells and tumour cells in the microenvironment of ALK-rearranged NSCLC require further study." (PMID 37371571, 2023). "We first determined the expression of cMet, ALK, and ROS1 in patient tumor tissue compared to tissue resection margin." (PMID 38144528, 2023). "In fact, tumor-cell-specific regional DNA hypermethylation is observed in both ALK+ ALCL and ALK– ALCL." (PMID 37894456, 2023). "Here, we collected tumour tissues from pretreated ALK-rearranged NSCLC patients, immunohistochemical staining was used to assess PD-L1 expression, and tumour-infiltrating immune cells were determined via multiplex immunofluorescence staining (mIF)." (PMID 37371571, 2023). "When the tumour progressed to MIA, the ALK fusion frequency was 2.3% (3/130), which was basically consistent with the ALK fusion frequency of 2.8% in IAC, p = 0.143." (PMID 36325966, 2023). "The pathological diagnosis was adenocarcinoma, and immunohistochemical analysis showed that the tumor cells were positive for CK7, NapsinA, ALK, and TTF-1." (PMID 36755262, 2023). "XIST+ tumor cells were most abundant in the IgG group, in which regulation of cell adhesion, the CXCR4 pathway, and ALK signaling in cancer were enriched." (PMID 37430270, 2023). "This revealed several strong putative interactions between GBM tumor cell ligands and macrophage receptors that were conserved over the different co‐cultures, including APP:CD74, CD99:PILRA, PTN:ALK, and CLU:TREM2." (PMID 37791581, 2023). "We found that the minimum amount of RNA needed for the detection of ALK, ROS1, RET fusion transcripts, and METΔex14 ranged between 1 and 10 pg·μL−1, corresponding to 0.1–0.01% fraction of tumor RNA." (PMID 37243883, 2023).
tumor (continued). "To explore the application of multi-target drugs in anti-tumor, we synthesized ten new dual-target inhibitors targeting EGFR and ALK simultaneously with ceritinib as the lead molecular." (PMID 36903251, 2023). "One future step could also be the enrichment of prognostic algorithms with molecular tumor features, such as the presence of the shorter and more oncogenic EML4-ALK fusion variant 3, which has been associated with earlier intracranial progression in TKI-treated ALK+ NSCLC." (PMID 37988952, 2023). "By coculturing tumor cell lines with PDF and testing the sensitivity of targeted therapy drugs, it was found that PDF affected the efficacy of EGFR and ALK inhibitors through different degrees of activation of HGF-MET and FGF-FGFR signaling pathways." (PMID 36911198, 2023). "After 9 days of ALK-TKI therapy, sequencing analysis was performed, which identified several tumor suppressor genes, such as NF2 or MED12, and multiple candidate genes." (PMID 37917191, 2023). "Further, our results identified potential ligand-receptor pairs (MDK/LRP1, MDK/ALK, GAS6/MERTK, and GAS6/AXL) for cell communication between these two types of cells and tumor cells." (PMID 37733241, 2023). "For half of the biomarkers (AKT, ALK, BRAF, EGFR, Hedgehog, HER2, KRAS, MSI, NTRK, and ROS1), depending on the tumor type, the response rate ranged from 0 to 100%." (PMID 36639625, 2023). "This NBNR group included neoplasias encompassing genetic fusion events involving tyrosine kinases (RET, NTRK, ALK, ROS, etc.)." (PMID 37510219, 2023). "Similar to alectinib, the mechanism of action of brigatinib involves the inhibition of ALK activity, which prevents the downstream activation of STAT3 and AKT, leading to decreased tumor cell viability." (PMID 37901797, 2023). "The results revealed that the NSCLC patients who harbored EGFR mutations or ALK rearrangements are associated with low objective response rates to anti-PD-1/PD-L1 therapy, which may be due to low rates of co-localized PD-L1 expression and CD8(+) tumor-infiltrating lymphocytes (TILs)." (PMID 37465684, 2023). "The tissue microarray (TMA) technique and immunohistochemistry were employed to identify the ALK (clone: 1A4 and D5F3) expression status in the tumor tissues." (PMID 37120571, 2023). "When the tumour progressed to MIA, the frequency of ALK fusion was 2.3% (3/130), which was basically consistent with the ALK fusion frequency of 2.8% in IAC, p = 0.143." (PMID 36325966, 2023). "ALK+ALCL also exhibits CpG Island methylation at STAT5A, a tumor suppressor that reciprocally suppresses NPM::ALK gene expression by binding to its enhancer." (PMID 37810974, 2023). "The majority of ALK+ ALCL cases (29/33, 88% for pSTAT3-Y705 and 30/33, 91% for pSTAT3-S727) and ALK- ALCL cases (14/22, 64% for pSTAT-Y705 and 19/22, 86% for pSTAT3-S727) expressed pSTAT3-Y705 and pSTAT3-S727 in more than 70% of tumor cells." (PMID 37388733, 2023). "Therefore, it was suggested that bevacizumab could stimulate the delivery of ALK TKI to the tumor." (PMID 37954850, 2023). "Inhibits will disrupt the ALK and ROS1- mediated signaling, further inhibiting the growing tumor cells in ALK and ROS1 cells." (PMID 37259442, 2023). "A recent study highlighted factors in the poor immune response of ALK+ NSCLC cancers such as cell‐specific differences in the presentation of immunogenic peptides and the tumour site." (PMID 37795653, 2023). "In 62 (16%) of the 393 patients with NSCLC, the tumor had EGFR (46, 12%), ALK (8, 2%) or BRAF V600E (8, 2%) targetable genomic alterations." (PMID 37370865, 2023). "Development of the model, incorporating patients’ clinical information such as tumor-lymph node-metastasis (TNM) staging and molecular biomarkers (ALK, EGFR, PD-1) will be followed and validated for large datasets that obtained from different institutions." (PMID 37081986, 2023).
tumor (continued). "Thus, a liquid biopsy-guided approach at progression in elderly patients with reduced PS and reduced tolerability for tumor rebiopsies may offer feasible and effective therapy guidance, as in this case where it disclosed the option of combining ALK- and EGFR-TKI." (PMID 37685884, 2023). "The notable immunohistochemical characteristics of these tumours are SMA expression and partial expression of desmin, vimentin and ALK." (PMID 36855132, 2023). "We and others have shown that ctDNA analysis in ALK + NSCLC can detect tumour-specific genetic alterations and copy number changes which correlate with tumour burden and clinical outcome." (PMID 37120670, 2023). "Confirmation of the diagnosis can be achieved through immunohistochemical staining for ALK, which is specific and positive in the nuclei of IMT tumor cells." (PMID 37902858, 2023). "For those low-quality and very limited samples, in situ approaches such as ALK IHC and ALK/ROS1/RET/NTRK FISH, which can also evaluate a small number of tumor cells, can be useful options." (PMID 37190044, 2023). "In this tumor type, CDK6 and FGFR2 were less expressed than in normal tissue, whereas CDK7, MET, ALK and AURKB stood out as upregulated in tumor samples." (PMID 36839989, 2023). "ROS1/TRK/ALK-TKI repotrectinib, in the PDX model, showed tumor-suppressive effects on both treatment-naïve and solvent-front-mutant ROS1-rearranged NSCLC." (PMID 36911198, 2023). "In Part 1 of the protocol, patients had tumor samples profiled with targeted next generation sequencing as well as immunohistochemistry for androgen receptor, HER‐2 and ALK." (PMID 37818869, 2023). "In the advanced tumor stages, patients with ACA had ALK fusions with 2.2% frequency (14/650), and the fusion partner was always EML4." (PMID 36293366, 2022). "Here we demonstrate that CD147 is a direct target of miR-146 and contributes to the survival and proliferation of ALK+ ALCL cells in vitro and to the engraftment and tumor growth in vivo in an ALK+ ALCL-xenotransplant mouse model." (PMID 35676454, 2022). "Recently, SMAD4 was reported to be phosphorylated at Tyr95 directly by ALK to elicit TGF-β gene transcription and tumour-suppressing responses." (PMID 35508387, 2022). "Meanwhile, new advances have emerged regarding the immunotherapy of ALK fusion cancers, such as combination regimens of immunosuppressive agents, tumor vaccines, ALK chimeric antigen receptor (CAR-T) therapy, adoptive T cell therapy, and ALK antibodies." (PMID 36591504, 2022). "After 10 months on alectinib, disease progression was observed, and treatment was switched to third-generation ALK TKI lorlatinib following current clinical standards, with ongoing tumor response for already 12 months." (PMID 35756632, 2022). "Due to CD147 involvement in multiple tumor-promoting mechanisms, CD147 has the potential to serve as a novel therapeutic target in ALK+ ALCL and warrants further investigation." (PMID 35676454, 2022). "For the first time, we focused on TLS in ALK+ tumors and evaluated immune cells in TLS and the tumor stroma independently." (PMID 36233802, 2022). "Numerous fusion oncoproteins have been identified in various tumor types, of which echinoderm microtubule-binding-like protein 4 (EML4)-ALK is the primary fusion product." (PMID 35978810, 2022). "Though ALK and ROS1 fusion proteins existed in multiple tumor types, ALK and ROS1 kinases inhibitors are only approved for ALK or ROS1‐positive NSCLC before July 14, 2022." (PMID 36254250, 2022).